BAG3 (BAG cochaperone 3)
Diseases named in the same sentence as BAG3 in open-access papers (continued):
Sharing a sentence is not in itself a finding about the gene and the disease.
melanoma (12 papers, 2013 to 2025). A malignant, usually aggressive tumor composed of atypical, neoplastic melanocytes. "Exposure to high temperature, oxidants, and other stressful factors causes the expression of anti-apoptotic protein BAG3 up-regulated in melanoma cells." (PMID 35936711, 2022). "Furthermore, BAG3 expression was reported to be associated with melanoma progression; more recently, an interesting correlation between BAG3 protein expression and prognosis in patients affected by metastatic melanoma with positive lymph nodes has been described." (PMID 29113311, 2017). "When KSR1 is lost, ERK activates the executioner Caspase 3 and inactivates the apoptosis antagonist BAG3 to promote apoptosis in our BRAFV600E-driven melanoma models." (PMID 37511580, 2023). "In vitro and in orthotopic xenografts, exposure to 50 Hz electromagnetic fields increases BAG3 levels in the human melanoma cell line M14." (PMID 35936711, 2022). "The same study also demonstrated that BAG3 serves to sustain protein levels of IKK-γ in melanoma cells, thereby allowing the continuous activation of the anti-apoptotic NF-ĸB pathway." (PMID 32121220, 2020). "In an in vivo model of human melanoma, BAG3 silencing resulted in a significant reduction in tumor growth and prolonged animal survival." (PMID 32121220, 2020). "BAG3 protein has been described for its anti-apoptotic role in melanoma cells and its expression in melanoma metastatic lymph nodes was correlated to the aggressiveness of the tumour." (PMID 29113311, 2017). "To this end, we analysed BAG3 expression in a series of tissue samples from tumours and metastasis coming from 41 patients with advanced malignant melanoma, by immunohistochemistry (IHC), using an anti-BAG3 monoclonal antibody (AC-1)." (PMID 29113311, 2017). "In a melanoma xenograft model, bag3 silencing indeed resulted in a significant reduction of tumour growth with subsequent prolonged animal's survival." (PMID 29113311, 2017). "In human melanomas, BAG3 positivity is correlated with the aggressiveness of the tumour cells and can sustain IKK-γ levels, allowing a sustained activation of NF-κB." (PMID 29113311, 2017). "We also demonstrated that, in melanoma cells, BAG3 is able to modulate the Hsp70- mediated delivery of the IKKγ subunit of IKK complex to proteasome, thereby sustaining NF-κB activation and inhibiting cell apoptosis." (PMID 29113311, 2017). "Those pieces of evidences suggest that BAG3 protein is involved in one of the major mechanism that sustain melanoma cells growth id est the axis BRAF/MEK/ERK." (PMID 29113311, 2017). "BAG3 is an anti-apoptotic protein that has been shown to sustain cell survival in a variety of tumour types, including melanoma." (PMID 29113311, 2017). "Here we show that BAG3 down-modulation interferes with BRAF levels in melanoma cells and sensitizes them to Vemurafenib treatment." (PMID 29113311, 2017). "We also analysed in the same experimental settings cleaved caspase-3/7 contents and we confirmed that interfering on BAG3 protein expression sensitizes to apoptosis melanoma cells subjected to a prolonged treatment with Vemurafenib." (PMID 29113311, 2017). "The clinical behavior of a subgroup of stage III melanoma patients has been revealed to be influenced by BAG3 expression." (PMID 28680391, 2017). "Recently, we reported that BAG3 levels in melanomas appeared to be specifically expressed in the cytoplasm of neoplastic cells while normal skin and benign nevi were negative." (PMID 29113311, 2017). "In conclusion, our data strongly support the idea that BAG3 can represent a valid target in the treatment of BRAF inhibitor resistant metastatic melanomas." (PMID 29113311, 2017). "These pieces of evidence prompted us to deeper analyse a possible involvement of BAG3 in melanoma tumour development." (PMID 29113311, 2017).
melanoma (continued). "Strikingly, it was reported that 50 Hz MF inhibited melanoma cell survival and reversed resistance to therapy through up-regulation of the anti-apoptotic protein BAG3 in melanoma cells." (PMID 24314291, 2013). "It has been shown that BAG3 co-localizes in the nucleus of melanoma cells with HSC70/HSP70, HSP90 and ORF29p, a LAP (latency associated protein) produced by Varicella Zoster Virus." (PMID 23876161, 2013). "Toward the elucidation of mechanisms by which resistance develops in treatment-resistant melanomas, we think that a contribution to this issue may be provided by the assessment of the role of BAG3 in response to therapy in melanoma cells." (PMID 29113311, 2017). "Thus, we firstly investigated if BAG3 and BRAF protein interacts in A375 melanoma cells that harbour BRAFV600E mutation." (PMID 29113311, 2017). "A375VR#6 clone was used to deeper investigate the molecular mechanisms through which BAG3 silencing could restore sensitivity to Vemurafenib in melanoma cells with acquired resistance to this inhibitor." (PMID 29113311, 2017). "BAG3 down-regulation appears to indeed induce cell apoptosis and impair tumour growth in melanoma - both in vitro and in vivo - suggesting that it may represent a novel target for tumour therapy." (PMID 29113311, 2017). "It has been indicated that the role of BAG3 in melanoma is due to its anti-apoptotic properties; in fact, this protein has been shown to protect melanoma cells from death through the interaction with apoptosis-regulating proteins, such as the IKKγ subunit of the NF-κB-activating complex IKK." (PMID 29113311, 2017). "Thus, the analysis of BAG3 expression in melanoma metastatic lymph nodes biopsies was proposed to potentially contribute to cancer prognosis." (PMID 28680391, 2017). "As BAG3 protein is involved in sustaining BRAF levels and ERK phosphorylation in A375 melanoma cells, we sought to verify if BAG3 silencing can affect the response of those cells to prolonged Vemurafenib treatment." (PMID 29113311, 2017). "In a previous report, we did not observe any significant changes in BAG3 positivity distribution between BRAF WT and BRAF mutated melanoma samples of primary tumours." (PMID 29113311, 2017). "Targets of the PI3K pathway were also found to be significantly dephosphorylated in cells where BAG3 was silenced such as AKT, mTOR and the p70S6K that also were found to be interesting targets to overcome acquired resistance to to BRAFV600E inhibition in melanoma." (PMID 29113311, 2017).
hepatocellular carcinoma (10 papers, 2014 to 2026). A malignant tumor that arises from hepatocytes. "BAG3 is also highly expressed in human hepatocellular carcinoma (HCC), promoting aggressive tumor growth behavior such as invasive growth and neoangiogenesis in these tumors." (PMID 32121220, 2020). "Bcl-2 associated athanogene 3 (BAG3) directly interacts with G6PD and consequently inhibits its dimerization and activity, leading to suppression of the PPP flux and the proliferation of hepatocellular carcinomas (HCCs)." (PMID 35207558, 2022). "Recently, it has been found to cause tumour progression in hepatocellular carcinoma (HCC) through methylating and stabilising BCL2-associated antiapoptotic gene 3 (BAG3)." (PMID 41562074, 2025). "Indeed, BAG3 is over-expressed in several neoplastic cell types and solid tumors including breast cancer, human hepatocellular carcinoma (HCC), glioblastomas, and pancreatic adenocarcinomas, where its high expression levels are correlated with a poor prognosis." (PMID 35163936, 2022). "Notably, the METTL21A inhibition has been shown to revitalize BAG3 degradation, trigger M1 macrophage reprogramming, and improve the efficacy of sorafenib, which offers the novel combined Methylation and molecular chaperone intervention approach to the treatment of hepatocellular carcinoma." (PMID 41562074, 2025). "BAG3 suppressed the PPP flux, de novo DNA synthesis and cell growth in hepatocellular carcinomas (HCCs)." (PMID 26621836, 2016).
neuropathy (10 papers, 2015 to 2025). A disorder affecting the nervous system that manifests with pain, tingling, numbness, and/or muscle weakness. "Moreover, mutations in HSPB8 and BAG3 have been reported to be associated with neuropathy and myopathy." (PMID 33168630, 2021). "Mutations in BAG3 and aberrations in its expression cause fulminant myopathies, presenting with progressive limb and axial muscle weakness, and respiratory insufficiency and neuropathy." (PMID 26545904, 2015).
cervical cancer (8 papers, 2020 to 2025). A primary or metastatic malignant neoplasm involving the cervix. "For instance, BAG3 and VEGF-A induced the proliferation and invasion of cervical cancer cells, and BAG3 and VEGF-A were direct target genes of miR-206 in cervical cancer." (PMID 34746018, 2021). "MiR-206 restrained the proliferation and motility of cervical cancer cells through targeting BAG3." (PMID 33526034, 2021). "In cervical cancer, BAG3 expression was shown to correlate with tumor grade." (PMID 32121220, 2020). "Additionally, siRNA-mediated depletion of BAG3 inhibits epithelial-mesenchymal transition (EMT) in cervical cancer cell lines in vitro and reduced tumor sizes in xenograft mouse model in vivo." (PMID 32121220, 2020). "Notably, BAG2 expression was significantly reduced in cervical cancer, while no significant changes were observed in other BAG family members (BAG1, BAG3, BAG4, BAG5, and BAG6), suggesting a unique role for BAG2 in cervical cancer." (PMID 40364789, 2025). "We discovered that miR-206 could inhibit the expression of both BAG3 and VEGF-A in CDDP-resistant cervical cancer cells." (PMID 34746018, 2021).
leukemia (8 papers, 2010 to 2024). A malignant (clonal) hematologic disorder, involving hematopoietic stem cells and characterized by the presence of primitive or atypical myeloid or lymphoid cells in the bone marrow and the blood. "Up-regulation of Bcl-2 and other anti-apoptotic genes (Bcl-xl, Bcl-2L10, Bag3 and Iap2/Birc3) have been also documented in Bu-resistant leukemia cell lines, which are capable of evading busulfan mediated G2-arrest and apoptosis." (PMID 38321093, 2024). "In cells from patients with leukemia, downregulation of BAG3 led to a rapid increase in apoptosis and an enhanced response to chemotherapeutic drugs." (PMID 36980278, 2023). "Previous studies demonstrated that the overexpression of BAG3 can inhibit apoptosis and promote the survival of certain types of leukemia cells." (PMID 30081850, 2018). "Furthermore, diethylmaleate-induced ROS-formation combined with BAG3-knockdown (siRNA) induced apoptosis in vitro in leukemia cells, but also in PBMCs." (PMID 32121220, 2020). "Cesaro concluded that WT1 enhances expression of BAG3, which contributes to the prosurvival role of WT1 in leukemia." (PMID 36980278, 2023). "In the past, we showed that ART induced apoptosis in KG-1a leukemia cells, and that a number of apoptosis-regulating genes (LOC51272, CIDEB, PDCD2, BAG1, BAG3, MADD) correlated with cellular responses towards ART." (PMID 20428086, 2010). "Studies has confirmed that overexpressed BAG3 could reverse the pro-apoptotic effect of WT1 silencing and regulate the leukemia stem cell-supporting activity." (PMID 36727051, 2022). "Indeed, the expression of BAG3 protein in CAF subtypes within the leukemic stroma is worthy of further investigation and could have significant implications for the development of tailored treatment methods aiming at interrupting the supporting network that drives leukemia progression." (PMID 39198407, 2024).
Parkinson disease (8 papers, 2012 to 2024). A progressive degenerative disorder of the central nervous system characterized by loss of dopamine producing neurons in the substantia nigra and the presence of Lewy bodies in the substantia nigra and locus coeruleus. "Genetic variants of BAG3 have been reported to be involved in Parkinson’s disease." (PMID 33080834, 2020). "BAG3 is considered crucial for selective autophagy, with significance in CNS diseases, particularly misfolded protein–related diseases such as AD and Parkinson disease." (PMID 37606039, 2023).
diabetes (7 papers, 2015 to 2025). "Our results implicated diabetes exacerbated IR-induced myocardial dysfunction through downregulated BAG3/Bcl-2/Nrf-2/HO-1 expression, increased p22/p67/caspase 3/PARP/apoptosis-mediated oxidative injury and impaired microvascular reactivity." (PMID 32751309, 2020). "Since the excessive proliferation and migration of VSMCs is an important pathogenesis of vascular remodeling in diabetes, the role of BAG3 in the excessive proliferation and migration of VSMCs and its molecular mechanism deserve further investigation." (PMID 38664681, 2024). "To understand the physiologic consequence of BAG3 overexpression in ischemic limbs of mice with diabetes, we evaluated perfusion recovery, the extent of limb injury and limb function in these mice." (PMID 36142618, 2022). "We evaluated the physiologic effect of replenishing BAG3 in ischemic skeletal muscles of mice with diabetes." (PMID 36142618, 2022). "To explore the possible role of reductive stress in diabetes and myocardial IR injury, we thus determined several defense antioxidants including BAG3, Bcl-2, Nrf-2 and HO-1 expression of the heart in response to diabetes and myocardial IR injury." (PMID 32751309, 2020). "Our present data evidenced that diabetes decreased BAG3, Bcl-2, Nrf-2 and HO-1 expression, further reduced myocardial IR-depressed BAG3, Bcl-2, Nrf-2 and HO-1 expression and increased cleavage caspase 3/PARP, leading to apoptosis formation in the heart." (PMID 32751309, 2020). "We explored the effect of STZ-induced diabetes and myocardial IR on cardiac BAG3 expression by Western blotting and immunohistochemistry." (PMID 32751309, 2020). "Therefore, we first examined the diabetes effect on BAG3 expression and the vasoreactivity of mesenteric arterioles in response to vasoconstrictors or vasodilators." (PMID 32751309, 2020). "We explored whether diabetes diminished BAG3/Bcl-2/Nrf-2/HO-1-mediated cardioprotection and overproduced oxidative stress contributing to exaggerated IR injury." (PMID 32751309, 2020). "In particular, beta cells of diabetics exhibited decreased expression of genes encoding molecular chaperones belonging to the heat shock families Hsp70 (HSPA1B, HSPA7, and HSPA8) and Hsp90 (HSP90AA1 and HSP90AB1) as well as co-chaperones (BAG3 and ST13) and nucleoporins (NDC1, NUP160, and POM121C)." (PMID 37569434, 2023). "Interestingly, the down-regulation of BAG3 in beta cells was found to increase insulin secretion in response to glucose stimulation, and in this context, the decreased levels of BAG3 mRNA in diabetics may be required for facilitating insulin secretion." (PMID 37569434, 2023). "Hence, we hypothesized that replenishing BAG3 would im-prove autophagy and reduce necroptosis in ischemic skeletal muscles in mice with diabetes." (PMID 36142618, 2022). "Moreover, in our in vivo preclinical model of PAD with diabetes, ischemic diabetic GAs showed less BAG3 expression and higher expression of necroptosis markers, whereas overexpression of BAG3 in ischemic diabetic GAs resulted in lower expression of necroptosis markers." (PMID 36142618, 2022). "However, it is still uncertain whether the protective role of BAG3 was affected in response to diabetes or myocardial IR injury." (PMID 32751309, 2020). "Moreover, further studies should be performed to clarify whether BAG3 alterations can contribute to diabetes pathogenesis." (PMID 25766323, 2015). "In this study, BAG3 gene was manipulated in smooth muscle to acquire SM22αCre; BAG3FL/FL mice and streptozotocin (STZ) was used to simulate diabetes." (PMID 38664681, 2024). "Nevertheless, our knowledge about the role of BAG3 in the regulation of ischemic skeletal muscle injury is limited, and whether BAG3 plays a role in the more severe ischemic limb injury associated with diabetes is not known." (PMID 36142618, 2022).
diabetes (continued). "Finally, our study explored the response of the cardiac endogenous defense mechanism in BAG3/Bcl-2/Nrf-2/HO-1 and NADPH oxidase p22/p67-mediated oxidative stress in response to diabetes and myocardial IR injury." (PMID 32751309, 2020). "Although it is well known that diabetes contributes to coronary artery spasm and myocardial ischemia in patients, the pathophysiologic role of BAG3 on resistant arterioles and cardiomyocytes has not yet been determined." (PMID 32751309, 2020).
viral infection (7 papers, 2010 to 2025). "In a previous study we demonstrated that JCV T-Ag inhibits expression of Bag3, a member of the Bag, Bcl-2-associated athanogene) family of molecular co-chaperone proteins, during the course of productive viral infection of glial cells by suppressing transcription of the Bag3 promoter." (PMID 22984599, 2012). "In addition, myocarditis and acute onset DCM in BAG3 carriers may be precipitated by viral infections through P38 signaling pathways, causing inflammation and apoptosis." (PMID 41250780, 2025). "The interaction between BAG3 and PPxY motif containing viral proteins is a well-defined event that occurs during a viral infection." (PMID 32365661, 2020). "This suggests that potentially undefined mechanism does exist in antagonizing pUL56-induced BAG3 degradation during viral infection." (PMID 32365661, 2020). "Our analysis in IMR-90 fibroblasts (which convinced us of the need to study EBNA3s in the context of virus infection) identified a selection of chaperones and their regulator BAG3 as EBNA3A targets." (PMID 21085583, 2010). "C1QTNF7 is also part of the interaction network of the BCL-2 athanogene 3 (BAG3), which plays multiple roles in physiological and pathologic processes, including antiapoptotic activity, signal transduction, virus infection, cell adhesion and migration, and initiation of autophagy." (PMID 32650713, 2020). "BAG3 is a stressor-response gene that has been reported to be modulated by a series of stress-inducers including high temperature, heavy metals, oxidative stress, and viral infection." (PMID 32365661, 2020). "During viral infection, the SARS-CoV significantly upregulates BAG3, but HSV1 does not substantially alter BAG3 within 12 h at the protein level." (PMID 32365661, 2020).